KLF15 (KLF transcription factor 15)
Diseases named in the same sentence as KLF15 in open-access papers (continued):
Sharing a sentence is not in itself a finding about the gene and the disease.
Arrhythmia (3 papers, 2013 to 2025). Any cardiac rhythm other than the normal sinus rhythm. "Klf15 then regulates the circadian expression of Kv channel-interacting protein 2 (KChIP2) thus leading to a daily change of susceptibility to heart arrhythmia." (PMID 23468616, 2013). "However, when the circadian rhythm is disturbed or KLF15 is deficient, the ion channels of the heart become dysregulated, leading to the occurrence of arrhythmia and laying a hidden danger for the occurrence of myocardial infarction." (PMID 40429972, 2025). "Moreover, as an upstream regulator of KChIP2, KLF15 transcriptionally controls rhythmic expression of KChIP2, and either deficiency or excess of KLF15 leads to loss of rhythmic QT variation, abnormal repolarization and increased vulnerability to arrhythmias." (PMID 33809104, 2021). "The findings indicate KLF15 as a new causative gene responsible for AF as well as ventricular arrhythmias and hypertrophic cardiomyopathy, and they provide novel insight into the molecular mechanisms underlying cardiac arrhythmias and hypertrophic cardiomyopathy." (PMID 33809104, 2021).
cervical carcinoma (3 papers, 2023 to 2024). A carcinoma arising from either the exocervical squamous epithelium or the endocervical glandular epithelium. "The role of miR-152-3p and KLF15 in regulating cervical cancer radioresistance was detected by cell activity assays." (PMID 37936130, 2023). "Besides the ZNF281 protein, long non-coding RNA (lncRNA) ZNF281 was also reported to be involved in the malignant progression of various malignant disorders, including cervical carcinoma, by targeting Kruppel-like factor 15 (KLF15)." (PMID 39518154, 2024).
dyslipidemia (3 papers, 2016 to 2025). "As such, the KLF15 ZnF domain is a compelling target for therapeutic interventions in metabolic syndromes, especially T2DM." (PMID 40411314, 2025). "Krüppel‐like factor 15 (KLF15) is a transcription factor contributing to the pathophysiology of multiple diseases, including metabolic syndromes." (PMID 40411314, 2025). "Many studies have demonstrated the role of KLF15 in the pathophysiology of multiple diseases, including metabolic syndromes." (PMID 40411314, 2025). "In summary, our research offers structural insights into the KLF15 ZnF–DNA interaction, which could potentially be instrumental in developing compounds for treating metabolic syndrome, including T2DM." (PMID 40411314, 2025). "The findings suggest that, in obese status, the lower expression level of A2bAR, KLF4, and KLF15 of visceral adipose tissue may correlate with obese-dyslipidemia induced inflammation in Uygur population." (PMID 27199507, 2016).
fibrosis (3 papers, 2021 to 2024). the formation of excess fibrous connective tissue in an organ or tissue in a reparative or reactive process. "Furthermore, Klf15 overexpression in Mrps5cKO mice hearts significantly suppressed cardiac fibrosis." (PMID 36949106, 2023).
glioma (3 papers, 2022 to 2024). A benign or malignant brain and spinal cord tumor that arises from glial cells (astrocytes, oligodendrocytes, ependymal cells). "In vitro, exogenous KLF15 had the ability to block miR-376a-3p effects on regulating glioma cell properties." (PMID 35071748, 2022). "In addition, miR-376a-3p is associated with lymphatic metastasis in gliomas and attenuates glioma metastasis by negatively regulating KLF15 expression." (PMID 38730506, 2024). "KLF15 was reported to be involved in the growth of glioma, and this was controlled by miR-376a-3p." (PMID 35071748, 2022).
hypertrophic cardiomyopathy (3 papers, 2021 to 2025). A condition in which the myocardium is hypertrophied without an obvious cause. "In the current investigation, a novel heterozygous mutation of c.685A>T (p.Lys229*) in the KLF15 gene was discovered in a family affected with AF as well as ventricular arrhythmias and hypertrophic cardiomyopathy by WES and bioinformatic analysis." (PMID 33809104, 2021). "Hence, this KLF15 variant may predispose to AF as well as ventricular arrhythmias and hypertrophic cardiomyopathy, but there may be a number of compensating mechanisms that the authors have not investigated." (PMID 33809104, 2021).
ischemic cardiomyopathy (3 papers, 2018 to 2024). Ischemic cardiomyopathy is a cardiomyopathy in which a weakness in the muscle of the heart due to inadequate oxygen delivery to the myocardium with coronary artery disease being the most common cause. "Our data are consistent with a recent study highlighting increased cardiac EZH2 expression, as well as cardiac enrichment of known gene targets of EZH2, such as KLF15, in ischemic cardiomyopathy patients." (PMID 37491334, 2023).
left ventricular hypertrophy (3 papers, 2017 to 2024). Enlargement of the LEFT VENTRICLE of the heart. "In humans, metformin attenuated increased risk of left ventricular hypertrophy due to the AA allele of KLF15, which is an inducer of BCAA catabolism." (PMID 37302544, 2023). "To date, there are few data translating these findings to humans but we have recently identified that the AA genotype in the KLF15 SNP rs9838915, is associated with increased risk of left ventricular hypertrophy (LVH), consistent with the loss of function phenotype in mice." (PMID 37302544, 2023). "Deletion or inhibition of KLF15 reduces the suppression of pro-hypertrophic factors and the stimulation of fibrotic signaling pathways, resulting in Left Ventricular Hypertrophy (LVH) development." (PMID 38516000, 2024).
lung carcinoma (3 papers, 2022 to 2024). "The results showed that BMSC-EVs expressing miR-190a-5p could increase the content of miR-190a-5p in lung cancer cells and inhibit the mRNA and protein expression of KLF15, thereby inhibiting the migration and invasion of lung cancer cells." (PMID 35860555, 2022). "Among the KLFs, the clear promoting effects on lung cancer were KLF5, KLF7, KLF8, and KLF15, as well as KLF4 and KLF6, which have dual functions." (PMID 38560274, 2024). "In this paper, KLFs have been summarized via systematic reviews, with either a promoting (KLF4 ∼ KLF8, KLF15) or an inhibiting (KLF2 ∼ KLF6, KLK9 ∼ KLF12 and KLF17) roles, which should be useful to monitor lung cancer progression or understand its mechanisms." (PMID 38560274, 2024).
muscle atrophy (3 papers, 2022 to 2023). The loss of muscle tissue due to inactivity or disease. "Moreover, the contribution of the Piezo1/KLF15/IL-6 axis to immobilization-induced muscle atrophy identified in mice was validated with the use of biopsy samples of patients with cast fixation–induced skeletal muscle atrophy." (PMID 35290243, 2022). "ECR significantly inhibited the mRNA expression of REDD1 and KLF15 and protein expression of MAFbx and MuRF1 in DEX-induced muscle atrophy cells compared with DEX-only treated cells." (PMID 37834245, 2023).
muscular dystrophy (3 papers, 2014 to 2025). Muscular dystrophy (MD) refers to a group of more than 30 genetic diseases characterized by progressive weakness and degeneration of the skeletal muscles that control movement. "The loss of Klf15 exacerbates skeletal muscle phenotypes in mdx mice, a model for muscular dystrophy." (PMID 41303576, 2025). "Scientists have found that once the KLF15 gene (Krüppel-like factor 15) is activated, glucocorticoids frequently indicate improving muscular resistance and alleviating muscular dystrophy." (PMID 37886924, 2023). "KLF15 appears to be a promising research target in understanding how metabolism of proteins and lipids may contribute to muscle atrophy as well as its possible role in muscle wasting disorders such as types of muscular dystrophy." (PMID 24600395, 2014).
myocardial infarction (3 papers, 2023 to 2025). Gross necrosis of the myocardium, as a result of interruption of the blood supply to the area, as in coronary thrombosis. "Furthermore, WWP1 can catalyze K48-linked polyubiquitination and degradation by targeting KLF15, triggering excessive cardiomyocyte inflammation after myocardial infarction." (PMID 40429972, 2025). "Xialu’s study confirms that the inhibition of KLF15 ubiquitylation can effectively alleviate the apoptosis induced by the increase of WWP1 expression after myocardial infarction." (PMID 40429972, 2025). "The perspective of KLF15 and circadian rhythm provides new research direction and therapeutic ideas for the treatment of myocardial infarction." (PMID 40429972, 2025). "This shows that the external circadian rhythm can affect the rhythm of KLF15 through the core clock gene, and the circadian rhythm of KLF15 can affect the incidence of myocardial infarction, so there is a correlation between the three." (PMID 40429972, 2025). "The pivotal role of KLF15 in mediating circadian regulation of myocardial infarction (MI) underscores the profound influence of biological rhythms on cardiovascular health and disease." (PMID 40429972, 2025). "The morning peak incidence of myocardial infarction results from coordinated effects of arrhythmias, morning blood pressure surge, platelet activation, and inhibited fibrinolysis—all jointly regulated by core clock genes and KLF15." (PMID 40429972, 2025). "Is there a link between the onset of myocardial infarction and KLF15 and circadian rhythm?" (PMID 40429972, 2025). "Furthermore, upregulation of KLF15 expression after myocardial infarction has been shown to improve the damage." (PMID 40429972, 2025). "Thus, KLF15 can regulate the inflammatory response after myocardial infarction through various pathways such as NF-κB, MAPK, Twist2, and CTRP12." (PMID 40429972, 2025). "Moreover, overexpression of KLF15 alleviates cardiac dysfunction after myocardial infarction by inhibiting the P38/MAPK signaling pathway." (PMID 36593958, 2023). "Animal experiments have shown that inhibiting GCGR signaling improves branched-chain amino acid metabolism, enhances cardiac function after myocardial infarction, and attenuates cardiac remodeling by modulating the TAK1/p38 MAPK and KLF15/BCATm pathways." (PMID 41458542, 2025). "Up-regulation of KLF15 concentration by pharmacologic or non-pharmacologic therapies corrects KLF15 rhythm disturbances and improves cardiac function after myocardial infarction." (PMID 40429972, 2025). "In the course of myocardial infarction treatment, whether the circadian rhythm is normal or not, and whether the KLF15 expression is increased or not, play an indispensable role in the prognosis of the patients." (PMID 40429972, 2025).
myocardial ischemia (3 papers, 2019 to 2023). A disorder of cardiac function caused by insufficient blood flow to the muscle tissue of the heart. "Our data suggested that myocardial ischemia or hypoxia induced down-regulation of KLF15 expression in cardiomyocytes, led to cardiomyocyte inflammatory response." (PMID 36593958, 2023). "Here, we demonstrated that E3 ligase WWP1 targeting KLF15 in cardiomyocytes aggravated myocardial ischemia injury." (PMID 36593958, 2023). "Although further mechanistic experiments are required, we believe this observation highlights a convergence of multiple epigenetic mechanisms to control the transcriptional activity of KLF15 in response to cardiac ischemia." (PMID 30089854, 2019). "In addition, in rats subjected to a chronic myocardial ischemia model, resveratrol induced the expression of Krüppel-like factor 15 (KLF15), known to play a protective role in the ischemic myocardium." (PMID 30934670, 2019). "Cardiac ischemia also correlates with induction of EZH2, an epigenetic regulator that may coordinate with differential DNA methylation to suppress KLF15 and other downstream metabolic gene targets." (PMID 30089854, 2019).
Sepsis (3 papers, 2019 to 2023). Sepsis is defined as life-threatening organ dysfunction caused by a dysregulated host response to infection. "Interestingly, several of the genes linked to glucocorticoid signaling (Arl4d, Cdkn1a, Ddit4, Fkbp5, Gjb6, Il6ra, Klf15, Nfkbia, Rhob, Sdc4, Sgk1, Sult1a1, Tob2, Wipf3) and apoptotic process were still upregulated 4 days post-sepsis." (PMID 31278440, 2019). "However, our findings identify that excessive suppression of the KLF15-CBG module can be maladaptive, leading to unbridled inflammatory activation and decompensation during sepsis, despite the presence of significantly increased free corticosterone concentration in bulk plasma." (PMID 35263131, 2022).
steatosis (3 papers, 2013 to 2025). Increased lipid within the cytoplasm of cells. "Increased PGC1α expression in KLF15-/- liver may also play a causal role in protection against steatosis through enhancement of mitochondrial FAO." (PMID 24167585, 2013). "In Klf15−/− mice, enhanced fatty acid oxidation presumably due in part to inhibition of mTORC1 may protect the liver from steatosis." (PMID 29942807, 2018). "Thus, Klf15 deletion uncouples hepatic insulin resistance and steatosis from ER stress and inflammation in HFD-induced obesity." (PMID 29942807, 2018). "In the current study, we have found that KLF15-/- mice are protected against HFD and ER stress-mediated steatosis and it is likely that increased AMPK activity in KLF15-/- liver contributes to this phenotype through inhibition of mTORC1 activity and induction of PGC-1α expression." (PMID 24167585, 2013).
Ventricular arrhythmia (3 papers, 2013 to 2022). "A deficiency or excess of Klf15 perturbs rhythmic CM electrical activity and increases susceptibility to ventricular arrhythmias." (PMID 35602953, 2022). "A previous study found that Klf15-deficient mice showed perturbed CM rhythmic activity and were susceptible to ventricular arrhythmias, similarly to the effects seen in Fam64a TG mice, which were considered to reflect suppressed KChIP2 activity." (PMID 35602953, 2022).
acute kidney injury (2 papers, 2023). Sudden and sustained deterioration of the kidney function characterized by decreased glomerular filtration rate, increased serum creatinine or oliguria. "Regarding the kidney, recent studies showed that KLF2, KLF4, KLF5, KLF6, and KLF15 were distributed in glomeruli and renal tubules and played important roles in the occurrence and development of proteinuric glomerular diseases and acute kidney injury 28-32,53,54." (PMID 36632460, 2023).
aortic aneurysm (2 papers, 2023 to 2024). A ruptured aneurysm located in the wall of the proximal portion of the descending aorta proceeding from the arch of the aorta. "In this study, we focused on the functions of KLF15 in VSMCs as it is highly expressed in the VSMCs of healthy aortas but downregulated in the VSMCs of patients with aortic aneurysms, as evidenced by the public single-cell sequencing dataset (GSE155468)." (PMID 38582447, 2024).
esophageal cancer (2 papers, 2017 to 2018). A primary or metastatic malignant neoplasm involving the esophagus. "Five nucleoproteins MISP, KLF10, KLF15, PPP1R18, and RXRβ were identified by oligonucleotide trapping, as the binding factors on the TRE under TPA stimulation, and were expressed at varying expression levels in esophageal cancer." (PMID 29098164, 2017). "Furthermore, DUXAP8 is positively related to MAGEA4, GABRA3 expression, and negatively related to INPP5A, TIMP4 expression in esophageal cancer; LINC00460 is positively related to ITGA3, LAMC2 expression, and negatively related to FOXO4, KLF15 expression in esophageal cancer." (PMID 29926523, 2018). "Several nucleoproteins (MISP, KLF10, KLF15, PPP1R18, and RXRβ) have been identified by affinity chromatography and mass spectrometry and could respond to TPA stimulation and regulate LCN2 expression in esophageal cancer cells." (PMID 29098164, 2017).
Ewing sarcoma (2 papers, 2020 to 2025). A small round cell tumor that lacks morphologic, immunohistochemical, and electron microscopic evidence of neuroectodermal differentiation. "On the other hand, RREB1-silencing did not produce these co-regulatory effects, demonstrating that in Ewing sarcoma cells, KLF15, TCF4 and NKX2-2 together constitute an inter-connected circuitry." (PMID 33080033, 2020). "Expression of DOX-inducible shRNAs against either KLF15 or TCF4 potently inhibited xenograft growth of Ewing sarcoma." (PMID 33080033, 2020). "A CRC comprising TCF4, NKX2-2, and KLF15 was previously reported in Ewing sarcoma." (PMID 41444391, 2025). "Here, we tested the dependency of Ewing sarcoma cells on KLF15 and TCF4 in vivo." (PMID 33080033, 2020). "Indeed, NKX2-2 has been reported to promoting cell proliferation of Ewing sarcoma, however, the biological significance of either KLF15 or TCF4 had hitherto been unknown in this cancer." (PMID 33080033, 2020). "Indeed, NKX2-2 has been established as a tumor-promoting factor in Ewing sarcoma, but the functions of KLF15 and TCF4 remained hitherto unknown in this cancer." (PMID 33080033, 2020). "In Ewing sarcoma, a CRC including KLF15, TCF4, and NKX2-2 MTFs that cooperate with EWSR1::FLI1 was reported in A-673 and EW-8 cells." (PMID 41444391, 2025). "In fact, the shared changes account for almost half of all changes in every RNA-Seq of CRC TFs, strongly suggesting that KLF15, TCF4 and NKX2-2 coordinate to regulate the transcriptome of Ewing sarcoma cells." (PMID 33080033, 2020). "This is plausible given that KLF15 almost always cooperates with TCF4 and NKX2-2 in Ewing sarcoma in terms of genomic binding." (PMID 33080033, 2020). "Here, we identify and functionally validate a CRC ‘trio’ constituted by three transcription factors (TFs): KLF15, TCF4 and NKX2-2, in Ewing sarcoma cells." (PMID 33080033, 2020). "Formed by KLF15, TCF4 and NKX2-2, this CRC apparatus coordinates the gene expression programs, including lipid metabolism, PI3K/AKT and MAPK signaling pathways, in Ewing sarcoma cells." (PMID 33080033, 2020). "Consistent with mRNA expression, silencing EWS-FLI1 decreased protein level of KLF15, NKX2-2 and TCF4 in Ewing sarcoma cell lines." (PMID 33080033, 2020). "Phenotypically, similar to CRC factors in other cancer types, KLF15, TCF4 and NKX2-2 each shows strong pro-growth and pro-survival functions in Ewing sarcoma." (PMID 33080033, 2020). "Considering the prominent roles of CRC in controlling transcriptional network, we postulated that KLF15, TCF4 and NKX2-2 are required for the viability and proliferation of Ewing sarcoma cells." (PMID 33080033, 2020). "Taken together, these data demonstrate that KLF15, TCF4 and NKX2-2 coordinately promote the transcription of chief components of the PI3K/AKT and MAPK signaling pathways, thereby activating these pro-growth and pro-survival signaling cascades in Ewing sarcoma." (PMID 33080033, 2020). "The biochemical finding that KLF15 regulates lipid synthesis in Ewing sarcoma is not completely surprisingly given the established role of KLF15 in controlling lipid synthesis and fat storage in adipose tissues." (PMID 33080033, 2020). "In order to address this hypothesis, we modified a computational algorithm given the central role of EWS-FLI1, and identified a CRC ‘trio’ constituted by KLF15, TCF4 and NKX2-2 in Ewing sarcoma cells." (PMID 33080033, 2020). "Taken together, these results demonstrate that as CRC members, KLF15, TCF4 and NKX2-2 may positively co-regulate each other and promote the growth and survival of Ewing sarcoma cells." (PMID 33080033, 2020). "In addition to cooperating with EWS-FLI1 to co-amplify their own transcription through a CRC model, KLF15, TCF4 and NKX2-2 also exhibit prominent capability of co-regulating the epigenome of Ewing sarcoma cells." (PMID 33080033, 2020).
glomerular diseases (2 papers, 2019 to 2023). "KLF4, KLF6, and KLF15 were also shown to be expressed in glomerular podocytes, and their protein expression levels were significantly reduced in injured podocytes in proteinuria glomerular diseases 31-35." (PMID 36632460, 2023).